CASP6 (caspase 6)
Diseases named in the same sentence as CASP6 in open-access papers (continued):
Sharing a sentence is not in itself a finding about the gene and the disease.
Stroke (7 papers, 2011 to 2024). Sudden impairment of blood flow to a part of the brain due to occlusion or rupture of an artery to the brain. "Caspase-6 has recently emerged as an important player in neuronal dysfunction and degeneration and its activation has been linked to several neurodegenerative conditions such as AD, HD and stroke." (PMID 22140457, 2011). "Male MMP-3 KO stroke brains also exhibited downregulation of apoptosis-related genes such as Casp9, Casp7, Bmf, Casp1, Bid, Casp6, Casp3, Casp2, Fas, Casp4, and Casp8." (PMID 39000490, 2024). "We previously found that neuronal cl-caspase-6 led to neurodegeneration in a stroke model and in RGC in a model of optic nerve crush." (PMID 36347836, 2022). "In the ischemic penumbra, Caspase-3 and Caspase-6 upregulation was detected in neurons 1–4 hours after stroke." (PMID 33995012, 2021). "Following adult stroke, caspase-6 knockout mice appeared to be protected, with reduced axonal degeneration and an improvement in functional outcome." (PMID 25823427, 2015). "Caspase-6, an effector caspase, has been widely researched in neurodevelopmental disorders and found to be important following adult stroke, but its function in the neonatal brain has yet to be detailed." (PMID 25823427, 2015). "Furthermore, deregulated activation of caspase-2, caspase-3, and caspase-8 contributes to the exacerbation of liver disease injury, while caspase-1, caspase-3, and caspase-6 knockout protect against stroke." (PMID 39625520, 2024). "Furthermore, female MMP-3 KO stroke brains showed decreased expression of apoptosis signaling genes Casp6, Tnfrsf1b, Tnfrsf1a, and Tnf, and downregulated expression of matrix metalloprotease genes Mmp14, Mmp9, and Mmp11." (PMID 39000490, 2024). "Although genetic knockout of caspase-1, caspase-3, and caspase-6 provides neuroprotection against stroke, one may ask whether apoptosis plays a critical role in ischemic stroke." (PMID 39625520, 2024).
colorectal cancer (6 papers, 2014 to 2025). A primary or metastatic malignant neoplasm that affects the colon or rectum. "Our results demonstrate the upregulation and activation of GSDMC2/3/4 by Caspase‐6 in colorectal cancer cells under Hypoxia and low‐glucose conditions." (PMID 40213993, 2025). "Activation of caspase-8 and caspase-9 led to activation of caspase-3, caspase-6, and caspase-7 and resulted in apoptosis of colorectal cancer cells." (PMID 33953834, 2021). "In addition, 5-FU chemoresponse to the classical colorectal cancer can be improved by silencing of stathmin via a caspase-6 (CASP6)-dependent signal." (PMID 27670291, 2016). "Casp6 is implicated in anoikis, and resistance to anoikis is a critical mediator of metastasis in cancer Unfortunately, the colorectal cancer AOM/DSS model is not metastatic, so the metastatic aspect of cancer could not be addressed in this paper." (PMID 25470254, 2014).
dementia (6 papers, 2013 to 2024). Loss of intellectual abilities interfering with an individual's social and occupational functions. "Pro-caspase-6 is observed in astrocytes after transient focal cerebral ischemia in rats, and active caspase-6 is localized together with GFAP in the brain of patients with HIV-associated dementia." (PMID 39001884, 2024). "Pro-caspase-6 is observed in astrocytes after transient focal cerebral ischemia in rats and active caspase-6 localizes with GFAP in the brain of patients with HIV-associated dementia." (PMID 31693684, 2019). "Based on the GO enrichment analysis, several antigens targeted by autoantibodies dysregulated in dementia were significantly enriched in GO terms of catalysis; CASP6 and CASP3 are particularly involved in endopeptidase activity." (PMID 38107644, 2023). "In adult DS cases with frank dementia as well as significant AD pathology, caspase 6 expression was strongly increased within the hippocampus." (PMID 23618225, 2013). "Thus, it is conceivable that caspase-6 cleavage of GFAP might add valuable information for the diagnosis and/or prognosis of dementia." (PMID 31693684, 2019).
leukemia (6 papers, 2014 to 2022). A malignant (clonal) hematologic disorder, involving hematopoietic stem cells and characterized by the presence of primitive or atypical myeloid or lymphoid cells in the bone marrow and the blood. "However, caspase-6 can cleave STAT1 to inhibit tumor cells in leukemia." (PMID 36675746, 2022). "Additionally, deleting caspase-3 and -7 can block both extrinsic and intrinsic apoptosis in human leukemia cells, but deleting caspase-3/-6 or caspase-6/-7 does not have any inhibitory effect on extrinsic or intrinsic apoptosis." (PMID 33426542, 2020).
ovarian carcinoma (6 papers, 2018 to 2023). A malignant neoplasm originating from the surface ovarian epithelium. "In most of ovarian cancer cell lines and tissues, the presence of active caspase-6 in the cytoplasm is associated with the loss of lamin A/C." (PMID 30450209, 2018). "Our investigation demonstrated an inverse association between active caspase-6 and lamin A in ovarian cancer cell lines and tissues." (PMID 30450209, 2018). "Our objective is to investigate the association between the loss of lamin A/C and the overexpression of caspase-6 in ovarian cancer cells." (PMID 30450209, 2018). "Overexpression and cytoplasmic localization of caspase-6 in ovarian cancer cells may be involved in lamin A degradation and deficiency observed in some ovarian cancer cells." (PMID 30450209, 2018). "However, some PYAGs with CNV gain, such as GSDMD, TP63, PRKACA, PJVK and CASP4, showed downregulated mRNA expression in ovarian cancers, and some PYAGs with CNV loss, such as IL18, GPX4, GZMA, NLRP6 and CASP6, showed upregulated mRNA expression in ovarian cancers." (PMID 36707884, 2023). "Capo-chichi and etal in study on Overexpression and cytoplasmic localization of caspase-6 showed that it is associated with lamin A degradation in set of high grade ovarian cancers showed that it may be involved in lamin A degradation and deficiency observed in some ovarian cancer cells." (PMID 31315664, 2019). "Overall, the overexpression and cytoplasmic localization of caspase-6 as well as degradation of lamin A/C in cancer cells seemed to be more associated to nuclear abnormalities initiating polyploidy, aneuploidy and chromosomal instability all of which are hallmarks for ovarian cancer." (PMID 30450209, 2018). "Our study showed that in ovarian cancer cell lines and in tumor tissues most of cleaved caspase-6 (active caspase-6) was localized to the cytoplasm while the expression of lamin A/C is absent." (PMID 30450209, 2018). "Immunohistochemistry was used to evaluate the expression of caspase-6 in set of ovarian cancer tissues previously reported to have lost lamin A/C." (PMID 30450209, 2018). "In some ovarian cancer cells, caspase-6 is overexpressed, and lamin A/C is underexpressed, thus it is thought caspase-6 may play a role in degrading lamin A/C in these tissues." (PMID 33316938, 2020). "provided a novel gene signature including 7 PRGs (AIM2, PLCG1, ELANE, PJVK, CASP3, CASP6, and GSDMA) for predicting the prognosis of ovarian cancer (OC) patients and laid a foundation for further studies of the relationships between PRGs and immunity in OC." (PMID 35912258, 2022). "From our study, we showed by immunoblotting, immunofluorescence, flow cytometry and immunohistochemistry that active caspase-6 was highly present in most ovarian cancer cell and tissues unlike normal ovarian epithelial cells or tissues." (PMID 30450209, 2018). "In our study, caspase-3 is absent while caspase-6 is overexpressed in ovarian carcinoma." (PMID 30450209, 2018). "Thus, the degradation of lamin A appears to be independent of caspase-6 in some ovarian cancer cell lines (A2780, OVCAR5 and OVCAR2) and suggested the existence of another route for lamin A degradation through phosphorylation by kinases perhaps." (PMID 30450209, 2018). "From our investigation active caspase-3 was absent in cells expressing cleaved caspase-6 as shown in some ovarian cancer cell lines or tumor tissues analyzed; meaning that caspase-6 activity initiates caspase-3 activation in cell apoptosis is disrupted in cancer." (PMID 30450209, 2018). "Thus, molecular events linking cleaved caspase-6 and lamin A/C degradation to apoptosis is uncoupled in most ovarian cancer cells probably due to the absence of caspase-3." (PMID 30450209, 2018).
nonalcoholic steatohepatitis (5 papers, 2022 to 2025). "A previous study shows that a choline-deficient high-fat diet (CD-HFD) can also reduce the phosphorylation level of AMPK and demonstrates the important role of the AMPK-Caspase 6 axis in nonalcoholic steatohepatitis." (PMID 35061665, 2022). "Caspase-6 activation induces liver damage in nonalcoholic steatohepatitis." (PMID 34862482, 2022). "Interestingly, some studies suggest that Fibroblast Growth Factor 4 may have a protective effect against nonalcoholic steatohepatitis (NAS) by suppressing the cleavage and activation of CASP6 via the AMP-activated protein kinase (AMPK) signaling pathway." (PMID 40427707, 2025).
viral infection (5 papers, 2014 to 2025). "Studies have found significant upregulation of caspase (CASP6), prostaglandin-endoperoxide synthase-2 (PTGS2), and interferon regulatory factor 7 (IRF7) with the pathological process initiated by a bacterial or viral infection." (PMID 39121644, 2024). "Studies have found significant upregulation of CASP6, PTGS2, and IRF7 with the pathological process initiated by bacterial or viral infection." (PMID 38393075, 2024).
bladder cancer (4 papers, 2021 to 2022). "This study showed that caspase-6 serves as a prognostic factor for bladder cancer, though further investigation is needed to explore the role of caspase-6 in the pyroptosis-related pathway as well as ascertain its clinical value." (PMID 35846123, 2022). "The Univariate Cox regression analysis revealed that eight PRGs (PRKACA, GSDMB, CASP9, GSDMD, CASP6, CASP8, AIM2, and CASP1) were significantly correlated with the prognosis in bladder cancer." (PMID 36120583, 2022). "Subsequently, the downstream effector caspases, including caspase-6 and caspase-7, were activated by MSSV treatment in both bladder cancer 5637 and T24 cells." (PMID 33430488, 2021).
Cerebral ischemia (4 papers, 2011 to 2019). Restriction of arterial blood supply to the brain associated with insufficient oxygenation to support the metabolic requirements of the tissue. "The presence of activated caspase-6 and cleavage of caspase-6 substrates is indeed a hallmark of AD, HD and cerebral ischemia, and has been shown in a number of different animal models and patient brain tissue." (PMID 22140457, 2011). "We hypothesize that caspase-6-generated fragments of GFAP (GFAP-C6) could reflect pathological processes underlying neurodegeneration as a function of ischemia of the brain resulting from a cardiac arrest (CA)." (PMID 31693684, 2019). "We see a significant increase in GFAP-C6 at 72 hours after CA suggesting that global cerebral ischemia affects processes related to the cleavage of GFAP by caspase-6." (PMID 31693684, 2019). "Only a few studies have investigated the effect of cerebral ischemia on the expression and activation of caspase-6 specifically." (PMID 31693684, 2019). "Similar experiments were carried out to evaluate whether CASP3 or CASP6 activation was dependent on CASP8: at 2 days after cerebral ischemia or 14 days after retinal ischemia, there was a significant reduction in the levels of CASP3 and CASP6 cleavage products in Z-IETD-FMK-treated rats (P<0.001)." (PMID 26539914, 2015). "Mechanistically, we showed that CASP6 or CASP8 inhibition (Z-VEID-FMK or Z-IETD-FMK) reduced the levels of cleaved procaspase-3 and procaspase-6 following cerebral ischemia." (PMID 26539914, 2015). "The activity of Casp6 in the AD brains is restricted to the cytoplasm and does not localize to the neuronal nuclei as in human cerebral ischemia, whereas Casp6 is both neuritic and nuclear in morphologically apoptotic neurons." (PMID 24265764, 2013).
glioblastoma (4 papers, 2017 to 2022). The most malignant astrocytic tumor (WHO grade IV). "Meanwhile, treatment with enzalutamide at 50 μM for 72 h led to 140% and 75% cascade activation of caspase-6 in human U87 MG and U87 MG-R glioblastoma cells, respectively." (PMID 36235203, 2022). "Sequentially, treatment with honokiol enhanced caspase-6 activity, a downstream target of caspase-3, in human drug-resistant glioblastoma cells." (PMID 32210117, 2020). "Successively, levels of cleaved caspase-3 and activities of caspase-3 and caspase-6 in human TMZ-tolerant glioblastoma cells were augmented following honokiol administration." (PMID 32210117, 2020). "However, pretreatment with Z-VEID-FM significantly attenuated enzalutamide-induced activation of caspase-6 in human drug-sensitive and -resistant glioblastoma cells by 75% and 100%, respectively." (PMID 36235203, 2022). "Interestingly, suppressing caspase-6 activity with its specific inhibitor concurrently protected human drug-sensitive and -resistant glioblastoma cells from enzalutamide-induced morphological shrinkage, DNA fragmentation, and apoptotic insults." (PMID 36235203, 2022). "Sequentially, caspase-6 activity in human U87 MG-R glioblastoma cells increased 2.5-fold." (PMID 34136065, 2021). "Honokiol can activate caspase-3 and caspase-6 in human drug-resistant glioblastoma cells." (PMID 32210117, 2020). "Instead, honokiol could stimulate activation of caspase-3 and caspase-6 in human drug-tolerant glioblastoma cells." (PMID 32210117, 2020). "Exposure to 50 μM enzalutamide, respectively, enhanced caspase-6 activities by 133% and 76% in human TMZ-sensitive U87 MG and TMZ-resistant U87 MG-R glioblastoma cells." (PMID 36235203, 2022). "Pretreatment with Z-VEID-FM at 50 μM did not affect the activities of caspase-6 in human U87 MG or U87 MG-R glioblastoma cells." (PMID 36235203, 2022).
Alexander disease (3 papers, 2019 to 2022). Alexander disease (AxD) is a rare neurodegenerative disorder of the astrocytes comprised of two clinical forms: AxD Type I and Type II manifesting with various degrees of macrocephaly, spasticity, ataxia and seizures and leading to psychomotor regression and death. "Ablation of caspase-6 is correlated with low levels of the pro-inflammatory cytokines TNF-α and IL-6 and astroglial cl-caspase-6 has been found in brain samples of patients with Alzheimer’s and Alexander’s disease." (PMID 36347836, 2022). "Astroglial caspase-6 is a key element in Alexander’s disease and known to mediate cleavage of the intermediate filament glial fibrillary acidic protein (GFAP)." (PMID 36347836, 2022). "Young patients with Alexander disease had high levels of GFAP breakdown products and caspase-6." (PMID 31682229, 2019).
Anxiety (3 papers, 2020 to 2024). Intense feelings of nervousness, tension, or panic often arise in response to interpersonal stresses. "Behavioral examinations of the 5xFAD mouse AD model with caspase-6-KO showed improved spatial learning, memory, and anxiety/risk assessment behavior." (PMID 37358955, 2023). "Together, these results indicate that Caspase-6 KO reduces risk assessment, and anxiety and memory-related behavior in female 5xFAD/C6-KO mice." (PMID 32050445, 2020). "Caspase-6 knockout in 5xFAD mice results in concurrent reductions in anxiety-like behavior and neuroinflammatory indicators compared to 5xFAD alone." (PMID 39703925, 2024). "Caspase-6 knockout in 5xFAD mice on the other hand has reduced Aβ pathology and improved performance in anxiety assessment compared to 5xFAD alone." (PMID 39703925, 2024).
chronic myelogenous leukemia (3 papers, 2016 to 2020). "Among them, downregulation of CASP6 induced suppression of the apoptosis of chronic myeloid leukemia cells." (PMID 32948197, 2020). "To confirm in vivo caspase-6-mediated processing of raptor, we used a caspase-6 knockout (KO) chronic myelogenous leukemia cell line (KBM-7) generated by gene trapping." (PMID 27551516, 2016).
epilepsy (3 papers, 2015 to 2024). A brain disorder characterized by episodes of abnormally increased neuronal discharge resulting in transient episodes of sensory or motor neurological dysfunction, or psychic dysfunction. "Our results showed that IRAK1 (P = 1.04 × 10−7), the targets of miR-146a, MAPKBP1 (P = 10.44 × 10−7) and CASP6 (P = 0.001), targets of miR-106b, were down-regulated, whereas MAP2K6 (P = 5.30 × 10−5), target of miR-194-5p, was up-regulated in epilepsy patients compared with normal controls." (PMID 25825351, 2015).
inflammatory bowel disease (3 papers, 2016 to 2025). A spectrum of small and large bowel inflammatory diseases of unknown etiology. "Further studies on the blockade of spinal CASP6 under painful pathophysiologic conditions such as bone cancer pain, sickle cell disease, or inflammatory bowel disease may represent another important therapeutic opportunity in analgesic development." (PMID 27781082, 2016). "Caspase 6 is a pivotal executioner caspase involved in cell death; however, its role in inflammatory bowel disease (IBD) remains incompletely understood." (PMID 41390757, 2025).
lung adenocarcinoma (3 papers, 2022). A carcinoma that arises from the lung and is characterized by the presence of malignant glandular epithelial cells. "Another comprehensive bioinformatics analysis also performed on lung adenocarcinoma identified a prognostic pyroptosis-related gene signature containing five genes (NLRP7, NLRP1, NLRP2, NOD1, and CASP6)." (PMID 36324154, 2022). "not only constructed a pyroptosis-related prognostic predication model involving 5 PRGs (CASP6, NLRP7, NOD1, NLRP1, and NLRP2) in lung adenocarcinoma, but also established a network of mRNA–miRNA–lncRNA closely relating to PRGs." (PMID 35912258, 2022).
neuroblastoma (3 papers, 2011 to 2017). Neuroblastoma (NB) is the most common solid, extracranial childhood tumor. "When we monitored the caspase activity in differentiated neuroblastoma cells expressing the caspase-6 (VEID) sensor treated with staurosporine we observed that the FRET intensity first decreased in the cell body and only 5-10 min later decreased in the neurites." (PMID 21605370, 2011).
Obesity (3 papers, 2024 to 2026). Accumulation of substantial excess body fat. "Here, we report that caspase-6 deficiency protects against high fat diet-induced obesity." (PMID 41969066, 2026). "In contrast, the adipogenesis genes COL12A1, FBN1 and RBP4, as well as the genes CASP6 and DPT that involved in inflammation or immune response, were downregulated in obese pigs but upregulated in obese human, consistent with previous reports showing their upregulation in obesity." (PMID 40658709, 2025).
prostate carcinoma (3 papers, 2015 to 2025). A carcinoma that arises from epithelial cells of the prostate gland. "Caspase 6 has been long identified as being associated with prostate cancer." (PMID 26243305, 2015). "This is the first published paper showing in vitro cancer cell suppression for prostate cancer with activation of caspase 6, as well as in vivo tumor suppression of prostate cancer in mice." (PMID 26243305, 2015). "Indeed, prior investigations have documented significant activation of caspase-6 and -7 in breast and prostate cancer-cell lines treated with DOX." (PMID 40864747, 2025). "The two clusters showed significant differences in the expression of PRGs; CHMP2A, CHMP4C, CYCS, CASP6, CASP8, GPX4, and TIRAP have high expression levels in cluster B, suggesting that these genes may associate with poor prognosis in prostate cancer." (PMID 35813821, 2022). "In fact, out of 107 prostate human adenocarcinomas analyzed, 61 % of prostate tumors had high caspase 6 activity, suggesting apoptotic deregulation may occur in early stages of prostate cancer." (PMID 26243305, 2015). "Thus, caspase 6 has been established as an important marker for prostate cancer." (PMID 26243305, 2015).